MAML2 (mastermind like transcriptional coactivator 2)
Description:
Acts as a transcriptional coactivator for NOTCH proteins. Has been shown to amplify NOTCH-induced transcription of HES1. Potentiates activation by NOTCH3 and NOTCH4 more efficiently than MAML1 or MAML3.
Synonyms: KIAA1819; MAM3; MAM-3; MAM2; MLL-MAML2
Tractability: No criterion of Open Targets' tractability assessment is met for any kind of drug.
Gene: Protein-coding gene on chromosome 11 (95,976,598 to 96,343,195, reverse strand). Ensembl gene ENSG00000184384.
Subcellular location: Nucleus speckle
Subcellular location (Human Protein Atlas): Nuclear bodies; Cytosol; Nucleoplasm
Pathways (Reactome):
Signal Transduction: NOTCH1 Intracellular Domain Regulates Transcription; NOTCH2 intracellular domain regulates transcription; NOTCH3 Intracellular Domain Regulates Transcription; NOTCH4 Intracellular Domain Regulates Transcription; Pre-NOTCH Transcription and Translation
Developmental Biology: Differentiation of naive CD4+ T cells to T helper 2 cells (Th2 cells); Formation of paraxial mesoderm; Regulation of gene expression in late stage (branching morphogenesis) pancreatic bud precursor cells
Disease: Constitutive Signaling by NOTCH1 HD+PEST Domain Mutants; Constitutive Signaling by NOTCH1 PEST Domain Mutants
Gene expression (Transcription): Notch-HLH transcription pathway; RUNX3 regulates NOTCH signaling
Gene Ontology:
Molecular function: protein binding; transcription coactivator activity
Biological process: Notch signaling pathway; positive regulation of transcription by RNA polymerase II; positive regulation of transcription of Notch receptor target
Cellular component: nuclear body; nucleoplasm; nucleus; nuclear speck
Genetic constraint (gnomAD): Loss-of-function variants: 22 observed, 101.87 expected, observed/expected ratio (o/e) 0.22, 90% interval 0.15 to 0.31. The upper end of that interval is the gene's LOEUF score, 0.31, which puts it in group 1 of 6, group 1 being the genes least tolerant of losing a copy. Missense variants: 1,321 observed, 1,389.9 expected, observed/expected ratio (o/e) 0.95, 90% interval 0.91 to 1. Synonymous variants: 547 observed, 518.84 expected, observed/expected ratio (o/e) 1.05, 90% interval 0.98 to 1.13.
Gene-disease validity (ClinGen):
ClinGen rates the evidence that MAML2 causes each of these diseases.
congenital heart disease (inheritance undetermined): No Known Disease Relationship. A heart disease that is present at birth.
Homologues: Orthologues: chimpanzee MAML2 (99% identical), macaque MAML2 (98% identical), rabbit MAML2 (90% identical), pig MAML2 (88% identical), dog MAML2 (85% identical), mouse Maml2 (84% identical), rat Maml2 (82% identical), guinea pig MAML2 (73% identical), tropical clawed frog maml2 (47% identical). Paralogues in human: MAML3 (25% identical), MAML1 (24% identical).
Diseases named in the same sentence as MAML2 in open-access papers:
MAML2 is named in the same sentence as 107 diseases in open-access papers, as found by Europe PMC text mining. Sharing a sentence is not in itself a finding about the gene and the disease. The quoted sentences say what the papers report.
mucoepidermoid carcinoma (72 papers, 2014 to 2026). A carcinoma morphologically characterized the presence of cuboidal mucous cells, goblet-like mucous cells, squamoid cells, cystic changes, and a fibrotic stromal formation. "Taken together, it seems that MAML2 rearrangements are exceedingly rare in WTs, and, when present, they likely indicate the presence of concurrent mucoepidermoid carcinoma, namely, the Warthin-like variant of it." (PMID 36752878, 2023). "A significant finding was the lack of enhancer activity in the MAML2 gene, linked to translocations (forming fusion genes such as CRTC1-MAML2, a known oncogenic driver in mucoepidermoid carcinoma), enhancer mutations, DNA methylation or histone acetylation changes, which downregulated MAML2." (PMID 40849356, 2025). "Therefore, the MAML2 split is an extremely useful auxiliary diagnostic tool that improves the positive diagnosis rate of mucoepidermoid carcinoma." (PMID 41216064, 2025). "Furthermore, mucoepidermoid carcinoma involves a MAML2 gene fusion, whereas MECA is associated with a PLAG1 gene rearrangement." (PMID 39479012, 2024). "Interestingly, the presence of CRTC1::MAML2 gene fusion in thymic mucoepidermoid carcinomas was associated with classic tumor histology, lower pT and TNM stage, and better overall survival." (PMID 38067300, 2023). "Moreover, MAML2-fused cases might be confused with variant or high-grade mucoepidermoid carcinomas, as they share squamous phenotype and MAML2 rearrangements." (PMID 41350449, 2025). "CRTC1 forms fusion transcripts with mastermind-like 2 (MAML2) that function as transcriptional coactivators driving mucoepidermoid carcinoma development, including in lungs." (PMID 40977688, 2025). "In this challenging case, we were able to diagnose the patient with mucoepidermoid carcinoma based on the MAML2 split identified in the FISH test." (PMID 41216064, 2025). "Histopathological analysis and MAML2 gene fluorescence in situ hybridization (FISH) testing confirmed the diagnosis of mucoepidermoid carcinoma." (PMID 41216064, 2025). "A MAML2 rearrangement was identified by FISH, thus confirming the diagnosis of oncocytic variant of mucoepidermoid carcinoma." (PMID 40088351, 2025). "In our case, only the CRTC1::MAML2 fusion found in molecular biology allowed us to make the differential diagnosis and conclude that it was a mucoepidermoid carcinoma." (PMID 39677248, 2024). "Salivary mucoepidermoid carcinoma (MEC) is a malignant salivary gland neoplasm characterized by mucous, intermediate and epidermoid (squamoid) tumor cells forming cystic and solid growth patterns, and usually associated with MAML2 gene rearrangement." (PMID 38217715, 2024). "In thymic tumors, MAML2 rearrangements can aid in the diagnosis, specifically in mucoepidermoid carcinoma." (PMID 38067300, 2023). "Studies in mice have confirmed CRTC1::MAML2 as an oncogenic driver for the development and maintenance of mucoepidermoid carcinomas." (PMID 38067300, 2023). "While CRCT1 was found to be fused with MAML2 in mucoepidermoid carcinomas, as in mucoepidermoid carcinomas elsewhere in the body, YAP1 was identified as the fusion partner of MAML2 in metaplastic thymomas and KMT2A in type B2 and B3 thymomas." (PMID 38067300, 2023). "MAML2 gene rearrangements have been detected in mucoepidermoid carcinomas, metaplastic thymomas, and occasional B2 and B3 thymomas." (PMID 38067300, 2023). "MAML2 can be highly expressed in B cell‐derived lymphomas, mucoepidermoid carcinomas, and chronic lymphocytic leukemia." (PMID 36464833, 2023). "Assessment of MAML2 by break-apart fluorescence in-situ hybridization, a highly sensitive and specific test for mucoepidermoid carcinoma, indicated that the tumor was intact." (PMID 35346255, 2022).
mucoepidermoid carcinoma (continued). "Previously, MAML2 has been reported to be upregulated and function as an tumor-activator in mucoepidermoid carcinoma and breast cancer." (PMID 33483471, 2021). "The oncogenic role of MAML2 was first described in mucoepidermoid carcinoma, in which a fusion oncogene MECT1-MAML2 that was involved in disrupting the normal cell cycle, differentiation and tumor development." (PMID 31652449, 2019). "Several studies have demonstrated MAML2 abnormal expression in various cancers, such as mucoepidermoid carcinoma, hidradenoma and breast cancer." (PMID 31652449, 2019). "The present study explored the significance of MAML2 rearrangement detected with FISH by using FFPE tissue sections of primary pulmonary mucoepidermoid carcinoma in a large series." (PMID 24714697, 2014). "Genomic studies of thyroid SMECE have so far been largely uninformative, showing a notable absence of MAML2 rearrangements characteristic of mucoepidermoid carcinoma or BRAF mutations." (PMID 39537991, 2025). "Mucoepidermoid carcinoma (MEC) is the most common malignant tumor of major and minor salivary glands characterized by mucous, intermediate, and epidermoid (squamoid) tumor cells forming cystic and solid growth patterns and usually associated with MAML2 rearrangement." (PMID 39537991, 2025). "MAML2, through CRTC1-MAML2 fusion, serves as a major oncogenic driver in mucoepidermoid carcinoma." (PMID 41363115, 2025). "MAML2-fusion test was not available in our laboratory at the time of the diagnosis to exclude the oncocytic variant of mucoepidermoid carcinoma." (PMID 38632256, 2024). "In the thymus, MAML2 rearrangements were first identified in mucoepidermoid carcinomas." (PMID 38067300, 2023). "MAML2 rearrangements are identified in 50 to 56% of thymic mucoepidermoid carcinomas." (PMID 38067300, 2023). "However, as MAML2 rearrangements are only identified in about half of mucoepidermoid carcinomas, caution must be practiced in its absence." (PMID 38067300, 2023). "The presence of MAML2 rearrangements aids in the diagnosis, specifically in high grade mucoepidermoid carcinomas, and can be utilized to distinguish mucoepidermoid carcinomas from thymic adenosquamous and squamous cell carcinomas as those do not harbor MAML2 rearrangements." (PMID 38067300, 2023). "Even in the UK, routine testing for MAML2 rearrangement in mucoepidermoid carcinoma has been the norm only since 2015–2016 with FISH the most widely available test, whereas MYB testing in adenoid cystic carcinoma is still only available in a handful of specialist centres." (PMID 35622296, 2022). "Similarly, CRTC1::MAML2 fusions have been described in mucoepidermoid carcinoma of various sites, whereas CRTC1::SS18 fusion has been implicated in a subset of undifferentiated small round blue cell sarcomas CMTCT have only been reported in CMTCT." (PMID 36726909, 2022). "Mucoepidermoid carcinoma (MEC) is often seen in salivary glands and can harbor MAML2 translocations (MAML2+)." (PMID 35457138, 2022). "However, in some situations it can be challenging to differentiate between a GOC and an intraosseous mucoepidermoid carcinoma and molecular testing for a MAML2 gene rearrangement may be useful in these circumstances." (PMID 33104949, 2021). "Nonetheless, considering the high concordance between FISH and RT-PCR, and the easy application of FISH method, we and other authors believed that FISH analysis of the MAML2 gene split might be more useful screening of a favorable subset of mucoepidermoid carcinoma cases." (PMID 24714697, 2014). "Additionally, a significant diagnostic pitfall is the ‘Warthin-like’ variant of mucoepidermoid carcinoma (WL-MEC), diagnosed by p63- and CK5/6-positive expression, added to the presence of MAML2 gene rearrangement." (PMID 41440486, 2025).
mucoepidermoid carcinoma (continued). "These include fusions of the ETV6 gene in secretory carcinoma (SC), MYB/MYBL1::NFIB in adenoid cystic carcinoma (AdCC), CRTC1/CRTC3::MAML2 in mucoepidermoid carcinoma (MEC), and EWSR1::ATF1 in hyalinizing clear cell carcinoma as the most frequent and best characterized gene fusions." (PMID 38217715, 2024). "For instance, in mucoepidermoid carcinomas, the reported fusion gene is cysteine-rich C-terminal 1 (CRTC1) leading to MAML2::CRTC1 fusions." (PMID 38067300, 2023). "Mastermind like transcriptional coactivator 2 (MAML2) is involved into the progression of many cancers, such as mucoepidermoid carcinoma and breast cancer." (PMID 33483471, 2021). "Another study confirmed the presence of MAML2 fusion in Warthin-like mucoepidermoid carcinoma, but in none of 114 WTs." (PMID 36752878, 2023). "A host of molecular defects have been demonstrated in ‘MAML2 translocation‐negative mucoepidermoid carcinoma’ in one study, but there was no mention of this SMECE subtype." (PMID 37305870, 2023). "Although the morphology and immunophenotype of the tumor suggested the diagnosis of mucoepidermoid carcinoma, fluorescence in situ hybridization failed to reveal the rearrangement of MAML2 gene, which is characteristic of mucoepidermoid carcinoma." (PMID 37274229, 2023). "Some reports highlighted the lack of MAML2 translocation in these tumors, as distinct from classical mucoepidermoid carcinoma (MEC) of the salivary glands." (PMID 37305870, 2023). "The presence of ‘squamous’ or ‘epidermoid’ areas and clear cells mimicking mucoepidermoid carcinoma can be potentially misleading; however, the absence of mucin, cytokeratin 7 expression and lack of MAML2 rearrangement can help exclude this possibility." (PMID 33351171, 2021). "Here, we report two female non-smoker patients diagnosed with low-grade mucoepidermoid carcinoma with oncocytic epithelium and prominent lymphoid (Warthin-like) stroma and with molecularly confirmed MAML2 rearrangement." (PMID 32222825, 2020). "MAML2 rearrangement was detected in both mucoepidermoid carcinoma cases, while all Warthin tumours were negative." (PMID 32222825, 2020). "Based on the results of fluorescence in situ hybridization, MAML2 gene rearrangement was not present in the typical portions of Warthin tumor and the mucoepidermoid carcinoma-like lesion." (PMID 30636634, 2019). "Salivary gland mucoepidermoid carcinoma (MEC) is a morphologically challenging tumor, harboring a canonical CRTC1/3:MAML2 fusion, if investigated." (PMID 40478494, 2025). "MAML2 fusion is absent in Warthin’s tumors, present in mucoepidermoid carcinoma." (PMID 38817461, 2024). "In addition, they suggested that high-grade tumours without the MAML2 rearrangement are probably high-grade non-mucoepidermoid carcinomas." (PMID 32222825, 2020). "However, mucoepidermoid carcinoma is often characterized by the fusion of the CRTC1 and MAML2 genes, which is not a feature of HCCC." (PMID 40738062, 2025).
meningioma (11 papers, 2021 to 2025). A generally slow growing tumor attached to the dura mater. "The rearrangement of MAML2 has been confirmed to be associated with a variety of diseases, such as atypical intraparenchymal meningioma and metaplastic thymoma." (PMID 40416971, 2025). "Clinical studies revealed that YAP fusion, particularly with MAML2, occurs in a subset of pediatric NF2-wildtype meningiomas, and the YAP1-MAML2 fusion is similar to NF2 mutant meningioma." (PMID 39894505, 2025). "Rare pediatric meningiomas have been recently identified to have YAP1::MAML2, YAP1::PYGO1, or YAP1::LMO1 gene fusions." (PMID 40491864, 2024). "NF2-mutant meningiomas and meningiomas with YAP1::MAML2 gene fusions share a gene expression profile, and meningioma in mice generated from YAP::MAML2 expression is phenotypically consistent with activated YAP expression." (PMID 40491864, 2024). "Furthermore, YAP undergoes frequent modifications, often through its fusion with other proteins, such as MLM-2, MAML2, PYGO1, and LMO1, in meningiomas and other types of tumors linked to neurofibromatosis type 2." (PMID 38001599, 2023). "Pediatric meningioma with the fusion of YAP1 and MAML2 genes is more likely to have pathological features of rhabdiod cells, which needs to be validated in large-scale studies for exploring better treatment under the integrated diagnosis." (PMID 36463108, 2022).
Poroma (11 papers, 2019 to 2025). A benign adnexal neoplasm composed of EPITHELIAL CELLS. "In Case 3, the fusion assay identified a YAP1-MAML2 fusion involving exon 4 of YAP1 and exon 2 of MAML2, similar to those reported in poromas." (PMID 31906059, 2019). "The studies so far raise interesting questions about why some fusion proteins seem to be specific to a particular disease, such as TAZ::CAMTA1 to EHE, whereas others are more permissive across a range of tumors, such as YAP::MAML2 to poroma, metaplastic thymoma, and glioblastoma, among others." (PMID 40491864, 2024). "Recent sequencing of these tumors demonstrated that 90% of poromas and ~70% of porocarcinomas exhibit YAP1 or WWTR1 gene fusions, with YAP1 fused to either MAML2 or NUTM1 and WWTR1 fused to NUTM1." (PMID 40491864, 2024). "Namely, YAP1-MAML2, MAML2-YAP-1, YAP1-NUTM1, and WWTR1-NUTM1 fusions were identified in 71, 48, 21, and 1 poromas, respectively." (PMID 37627947, 2023). "Most poromas and porocarcinomas harbor YAP1::MAML2/NUTM1 or, rarely, WWTR1::NUTM1 fusions." (PMID 41350449, 2025).
thymoma (10 papers, 2021 to 2024). A neoplasm arising from the epithelial cells of the thymus. "The detection of these diverse gene fusions underscores the potential utility of MAML2 gene rearrangements as prospective biomarkers for the morphological classification of thymomas." (PMID 37849766, 2023). "In metaplastic thymomas the fusion partner is Yes associated protein 1 (YAP1), leading to YAP1::MAML2 fusion genes." (PMID 38067300, 2023). "The MAML2 gene rearrangements were also studied in micronodular thymoma with lymphoid stroma and conventional type A thymoma, but no rearrangements were found in these types." (PMID 34354947, 2021). "Furthermore, Type B2 and B3 thymomas were rarely associated with KMT2A–MAML2 translocations involving different combinations of exons 8, 9, 10, or 11 of KMT2A, and exon 2 of MAML2 to varying extents." (PMID 38338833, 2024). "These two cases suggest that YAP1::MAML2 rearrangements may not only be found in pure metaplastic thymomas but also in more aggressive biphasic mediastinal tumors." (PMID 38067300, 2023). "Fusion with different gene partners suggests that MAML2 gene rearrangement may be a potential biomarker for the morphological classification of thymomas." (PMID 34354947, 2021). "Recently, it had been reported that there are high frequency Yes Associated Protein 1 (YAP1) - Mastermind Like Transcriptional Coactivator 2 (MAML2) fusions in an eight metaplastic thymomas cohort study, and the genetic alterations may be closely related to tumor occurrence or prognosis." (PMID 34354947, 2021). "Metaplastic thymoma is a rare biphasic thymic tumor with indolent behavior and recurrent YAP1::MAML2 gene rearrangement." (PMID 38864046, 2024). "In a subset of B2 and B3 thymomas the fusion partner is lysine methyltransferase 2A (KMT2A), resulting in KMT2A::MAML2 fusions." (PMID 38067300, 2023). "In metaplastic thymomas the fusion partner is YAP1, resulting in YAP1::MAML2 fusion genes fusing exon 1 or exons 1–5 on YAP1 with exons 2–5 on MAML2." (PMID 38067300, 2023). "MAML2 rearrangements have been identified in 6% of B2 and B3 thymoma but not in other thymomas." (PMID 38067300, 2023). "In contrast, YAP1::MAML2 fusions were not identified in type A thymoma or micronodular thymoma with lymphoid stroma, another entity that may be included in differential diagnoses of metaplastic thymomas." (PMID 38067300, 2023).
Warthin tumor (9 papers, 2019 to 2024). An adenoma characterized by an oncocytic, often papillary, epithelial component, dense lymphoid stroma, and cystic spaces. "Previous studies described MAML2 rearrangements in MEC of various sites, as well as in the metaplastic variant of cystadenolymphoma (Warthin tumor), although the MAML2 rearranged Warthin tumors may have been misclassified as Warthin-like MEC." (PMID 35457138, 2022). "Our study underscores the importance of a meticulous evaluation of both clinical and histological features, coupled with the detection of MAML2 rearrangement, as a credible method for distinguishing WL-MEC from other benign and malignant lesions, particularly metaplastic Warthin tumor." (PMID 38988706, 2024). "On the other hand, most of the recent studies did not report translocations involving MAML2 in Warthin tumours." (PMID 32222825, 2020).